RMRP (RNA component of mitochondrial RNA processing endoribonuclease)
Diseases named in the same sentence as RMRP in open-access papers (continued):
Sharing a sentence is not in itself a finding about the gene and the disease.
cancer (26 papers, 2014 to 2026). A tumor composed of atypical neoplastic, often pleomorphic cells that invade other tissues. "Several other non-polyadenylated transcripts, such as TERC (the RNA component of telomerase) and RMRP (an endoribonuclease implicated in cancer progression), were also highly differentially abundant in the rRNA- Dissociated samples." (PMID 37864274, 2023). "Like RPPH1, RMRP ncRNA is similarly overexpressed and associated with unfavorable prognoses across a multitude of cancer contexts, and evidence suggests RMRP also contributes to proliferation through novel protein interactions and miRNA sequestration." (PMID 36754845, 2023). "Based on the presence of the β-catenin/TCF and YAP/TBX5 constituents in the upper parts of the RMRP gene, expression of RMRP might be associated with the cancer-associated pathways, Wnt/β-catenin and Hippo/YAP." (PMID 33996836, 2021). "Mutations in the RMRP promoter led to enhanced nuclear protein binding to the promoter, consequently elevating transcription of RMRP, which might be associated with cancer progression." (PMID 34621748, 2021). "It has been reported that miR-1-3p can be silenced by several lncRNAs such as MALAT1, DANCR, and RMRP in cancers." (PMID 39061232, 2024). "Actually, RMRP is considered and identified as an emerging target in carcinogenesis and tumor therapy and is a potent regulator of metabolic reprogramming in cancer." (PMID 38722543, 2024). "Not only in ESCC, but RMRP dysregulation has also been addressed in other cancers and is commonly considered a promoter in tumor malignancy." (PMID 38722543, 2024). "One of the pathways being influenced RMRP is stem cells metabolism which accords with the formerly reported role of RMRP in giving permission to cancer cells for infinite proliferation via interplay with TERT." (PMID 33996836, 2021). "The RNA component of mitochondrial RNA-processing endoribonuclease (RMRP) was recently shown to play a role in cancer development." (PMID 34621748, 2021). "To explore the clinical relevance of RMRP in human cancers, we analyzed the TCGA database and found that the RMRP gene is amplified in multiple cancers." (PMID 34621748, 2021). "Brief reports of studies which assessed function of RMRP in cancer animal models (Δ: knock down or deletion)." (PMID 33996836, 2021). "Of note, knockout of RMRP via CRISPR-Cas9 achieved a more profound inhibitory effect on cancer cell growth, because RMRP expression was more markedly depleted in JIMT-1 cells." (PMID 34621748, 2021). "In several cancers, RMRP expression is increased, and RMRP downregulation leads to cell cycle arrest and apoptosis." (PMID 33846370, 2021). "Another study in this type of cancer has shown the role of RMRP in sequestration of miR-206 and activation of TACR1/Erk1/2 pathway." (PMID 33996836, 2021). "Rather recently, an additional role of RMRP in different types of cancer has been reported by multiple publications that describe a contribution of RMRP to, for example, cancer cell proliferation, migration, and invasion, by sponging up different miRNAs." (PMID 32340118, 2020). "At present, researches exploring the function of RMRP have focused on its function in the development of cancer, and the results show that lncRNA members can increase the proliferation and migration of cancer cells." (PMID 30926681, 2019). "RMRP has been claimed to have a pro-oncogenic role in many types of cancer cells." (PMID 41044334, 2025). "RMRP is reported to counteract the activities of numerous additional miRNAs, in all cases promoting cell proliferation, suggesting RMRP may also serve as a promising target for anti-cancer strategies." (PMID 36754845, 2023). "The sustained activation of Wnt/β-catenin signaling by RMRP might contribute to the better management of cancers." (PMID 34657141, 2021). "In addition to its role in the pathogenesis of CHH, RMRP participates in the pathogenesis of cancers." (PMID 33996836, 2021).
cancer (continued). "Recently, RMRP was also found to be involved in cancer development." (PMID 34621748, 2021). "Thus, both RMRP and SAMMSON are mitochondrial metabolic regulators with recurrent SCNAs due to focal amplifications, causally involved in cancer." (PMID 33329688, 2020). "Other replication studies could causally link mutations affecting lncRNAs, such as RMRP, NEAT1, or LINC-PINT, to cancer." (PMID 33329688, 2020). "Even though various mutations in the RMRP gene are linked to developmental defects and pathogenesis, its relevance to cancer etiology has not been well established." (PMID 26415221, 2015). "Similarly, RMRP can act as a sponge of miR-206 in other types of cancer." (PMID 34621748, 2021). "Moreover, up-regulation of RMRP is a marker of poor prognosis in these types of cancers." (PMID 33996836, 2021). "In addition, it will be interesting to test whether Pol II is involved in the transcription of the RMRP gene depending upon cellular context, such as in cancer cells." (PMID 26415221, 2015). "Moreover, common target genes activated by YAP and β-catenin, such as RMRP as shown here, could provide novel oncotargets for cancer therapeutics." (PMID 26415221, 2015). "The cell viability assay revealed that ectopic RMRP significantly increases cancer cell growth, while knockdown of AKT by two independent siRNAs blocks the tumor-promoting function of RMRP in JIMT-1 and BT549 cells." (PMID 34621748, 2021). "Of the top down-regulated genes, PLAGL1, CTH and VIM are positively correlated with HNSCC, while increased expression of RMRP, SULT1 and LTBP1 has been recorded in other cancers." (PMID 31827722, 2019). "Even though the RMRP gene is known to be transcribed by Pol III, more complex regulation is likely to be necessary for RMRP transcription in cancer cells." (PMID 26415221, 2015). "Here we explore the biogenesis, functions, and cancer connections for both RPPH1 and RMRP." (PMID 36754845, 2023). "In the present narrative review, we explain the role of RMRP in the development of cancers and some other non-malignant disorders." (PMID 33996836, 2021). "Elevated levels of RMRP have been observed in different cancers, in one case as a result of transcriptional activation of the RMRP gene by the Wnt pathway through binding of YAP and β-catenin to the TATA box of the RMRP promoter." (PMID 32611613, 2020). "However, in cancer cells Wnt stimulation increases the protein level of β-catenin and YAP in the nucleus and recruits them to the promoter regions of the RMRP gene via TCF4 and TBX5 DNA binding proteins, which leads to elevated transcription of RMRP." (PMID 26415221, 2015). "So we tested whether the oncogenic signaling pathways, Wnt/β-catenin and Hippo/YAP pathways, are relevant to the enhanced expression of RMRP in cancer cells because of the predicted β-catenin/TCF and YAP/TBX5 elements in the upstream regions of the RMRP gene." (PMID 26415221, 2015).
tumor (16 papers, 2015 to 2025). "All these papers, together with the support of this research, confirm the involvement of RMRP in tumor development by mediating malignant activities including glycolysis, proliferation, and apoptosis." (PMID 38722543, 2024). "In our study, we confirmed that aberrant RMRP expression patterns are related to tumor progression and are involved in cell migration and invasion processes both in vitro and in vivo." (PMID 37958478, 2023). "RMRP was found to be related to BLCA tumor progression and the cell migration and invasion processes via the miR-206/G6PD axis both in vitro and in vivo." (PMID 37958478, 2023). "Taken together, these results indicate that downregulated RMRP inhibited tumor growth in vivo and that body fluid RMRP was actively secreted from human gastric tissues." (PMID 27192121, 2016). "Indeed, different studies identify the lncRNAs CASC11, CCAT1 and RMRP as BC tumor promoters acting as ceRNA." (PMID 37238229, 2023). "Furthermore, we demonstrated that RMRP contributes to BLCA tumor progression via a novel ceRNA network: the miR-206/G6PD axis." (PMID 37958478, 2023). "RMRP might serve as a tumor promoter to accelerate cell proliferation, migration, and invasion of ESCC through regulating the miR-613/NRP2 axis." (PMID 34516335, 2021). "Knockdown of RMRP significantly inhibited tumor growth in a dose-dependent manner." (PMID 27192121, 2016). "Importantly, RMRP overexpression completely abolished miR-206’s tumor suppressive activity." (PMID 34621748, 2021). "Notably, a recent paper has emphasized the clinical association between lncRNA RNA component of mitochondrial RNA processing endoribonuclease (RMRP) and ESCC patients’ poor prognosis and tumor stage." (PMID 38722543, 2024).
skeletal dysplasia (6 papers, 2016 to 2026). Any Mendelian diseases that affects growth and development of the skeleton. "Mutations in the RMRP gene, encoding the essential RMRP snoRNA present in the RNase MRP macromolecular protein–RNA complex, are the cause of cartilage-hair hypoplasia-type human skeletal dysplasias." (PMID 30718282, 2019). "However, it is not clear why mutations in RMRP RNA lead to skeletal dysplasia." (PMID 28743979, 2017).
infection (2 papers, 2017 to 2019). The state of being infected such as from the introduction of a foreign agent such as serum, vaccine, antigenic substance or organism. "Other lncRNAs (i.e., BANCR, GAS5, GSTT1-AS1, PVT1, RMRP, and SNHG15) increased at one or more time-points during infection; BANCR was highly increased in infected cells, but only at 24 h." (PMID 31547203, 2019).
hematological malignancies (1 paper, 2021). "Taken together, RMRP is an lncRNA whose dysregulation and somatic mutations have been demonstrated in solid and hematological malignancies." (PMID 33996836, 2021).
RMRP also shares sentences with these, for which no sentence is quoted: colorectal cancer (3 papers); Hyperglycaemia (3); anemia (2); bone marrow failure (2); metaphyseal dysplasia without hypotrichosis (2); pancreatic cancer (2); adenocarcinoma (1); atherosclerosis (1); Autoimmunity (1); cognitive defects (1); combined-immunodeficiency (1); eosinophilia (1); gastrointestinal disorders (1); head-neck carcinoma (1); heart failure (1); hepatic veno-occlusive disease (1); Hirschsprung disease (1); hypertrophy (1); Hypoglycemia (1); hypospadias (1); lymphoma (1); Metaphyseal dysplasia (1); Obesity (1); pancreatic ductal adenocarcinoma (1); Perrault syndrome (1); short-limbed dwarfism (1); stomach adenocarcinoma (1); trisomy 21 (1); uterine corpus endometrial carcinoma (1).